FSTL1 (follistatin like 1)
Diseases named in the same sentence as FSTL1 in open-access papers (continued):
Sharing a sentence is not in itself a finding about the gene and the disease.
liver cancer (4 papers, 2018 to 2026). An epithelial or non-epithelial malignant neoplasm that arises from the liver. "FSTL1, identified as a key signaling molecule in our cSCC research, has been previously recognized for its crucial role in the progression of gastric and hepatic cancers." (PMID 38605354, 2024). "Next, several studies reported an antiapoptotic property of FSTL1 in many different cell types such as cardiomyocytes, dermal fibroblasts, neurons, endothelial cells, and lung and liver cancer cells." (PMID 30595761, 2018). "Follistatin-like 1 (FSTL1), a pro-inflammatory factor, which is found to be upregulated during inflammation, is predominantly secreted from the CAFs rather than liver cancer cells." (PMID 35971182, 2022).
lung adenocarcinoma (4 papers, 2017 to 2023). A carcinoma that arises from the lung and is characterized by the presence of malignant glandular epithelial cells. "Although loss of FSTL1 expression was shown to be a predictive marker of poor prognosis for lung adenocarcinoma in our study, it was reported to have contradictive roles in different kinds of tumor." (PMID 28852126, 2017). "In public dataset GSE31210, low FSTL1 RNA level was associated with lung adenocarcinoma patients with ALK-fusion or KRAS mutation compared to those with EGFR mutation or EGFR/KRAS/ALK triple-negative tumors." (PMID 28852126, 2017). "Decreased levels of FSTL1 have been found in various tumors compared to normal tissues and have been associated with poor clinical prognosis in patients with ovarian cancer, non-small cell lung cancer, especially with lung adenocarcinoma." (PMID 34440203, 2021). "Frequent decrease of FSTL1 expression in adenocarcinoma with KRAS mutation or ALK fusion and in smokers implies that FSTL1 has a critical role and may be a potential therapeutic target for some specific molecular types of lung adenocarcinoma." (PMID 28852126, 2017). "The FSTL1-BMP4-Smad signaling has been reported in lung adenocarcinoma and glioblastoma, but the role of FSTL1 in BMP4-Smad signaling remains controversial." (PMID 36756161, 2023). "For example, the IHC analysis and survival analysis of the public data both reveal a positive correlation between FSTL1 level and overall survival in lung adenocarcinoma patients." (PMID 36756161, 2023). "In lung adenocarcinoma of our patient cohort and public dataset, FSTL1 expression had positive correlation with BMP4-p-Smad1/5/8-Smad4 expression level and loss of FSTL1, BMP4, and Smad4 expression had a similar trend to predict poor prognosis." (PMID 28852126, 2017). "The prognostic value of FSTL1 in lung adenocarcinoma highlighted in our study indicates the need to decipher the mechanism of FSTL1-regulated cancer progression." (PMID 28852126, 2017). "Therefore, how FSTL1 modulates BMP4-Smad signaling pathway in lung adenocarcinoma should be clarified by further investigation." (PMID 28852126, 2017). "Lung adenocarcinoma patients with low FSTL1, BMP4, or Smad4 expression had poor prognosis." (PMID 28852126, 2017). "Low FSTL1 IHC expression retained its prognostic significance in lung adenocarcinoma (P = 0.018)." (PMID 28852126, 2017). "After revealing the prognostic role of FSTL1, BMP4, and Smad4 in lung adenocarcinoma, we further analyzed their expression correlations." (PMID 28852126, 2017). "Chiou and colleagues showed low expression of FSTL1 and BMP4 in lung adenocarcinoma." (PMID 36756161, 2023). "MiR-198 is also involved in suppressing colorectal cancer growth and lung adenocarcinoma A549 cell proliferation, but the relation between FSTL1 and miR-198 in this cancer type has not yet been studied." (PMID 29594389, 2018). "When stratified by different histological types, low FSTL1, BMP4, and Smad4 expression retained their trends in predicting poor prognosis in lung adenocarcinoma (LUAD) but not in lung squamous cell carcinoma (SCC)." (PMID 28852126, 2017). "In conclusion, current study revealed that low FSTL1, BMP4, and Smad4 expression significantly predict poor prognosis in lung adenocarcinoma but not in squamous cell carcinoma." (PMID 28852126, 2017).
lymph node metastasis (4 papers, 2016 to 2020). "In addition, the higher FSTL1 expression was associated with the infiltrating depth, lymph node metastasis and poor prognosis of CRC." (PMID 29844309, 2018). "In multivariate analysis, only low FSTL1 expression (hazard ratio [HR] = 2.55; 95% confidence interval [CI] = 1.04–6.24; P = 0.041) and lymph node metastasis (HR = 2.62; 95% CI = 1.26–5.46; P = 0.010) remained independently prognostic." (PMID 28852126, 2017). "In univariate analysis, low FSTL1 expression, lymph node metastasis, and distant metastasis were all significantly correlated with unfavorable overall survival." (PMID 28852126, 2017). "Since FSTL1 expression was related to CRC invasion depth and lymph node metastasis as described, trans-well and wound-healing assays were performed." (PMID 29844309, 2018). "These factors were subjected to multivariate analysis, which indicated that tumor size (P = 0.006), depth of invasion (P = 0.007), lymph node metastasis (P < 0.001), TNM stage (P < 0.001), and FSTL1 expression (P = 0.002) were independent prognostic factors in GC patients." (PMID 33292276, 2020).
metabolic syndrome (4 papers, 2019 to 2026). A cluster of metabolic risk factors for CARDIOVASCULAR DISEASES and TYPE 2 DIABETES MELLITUS. "The multimarker approach utilizing adiponectin, FSTL1, and irisin demonstrates high diagnostic performance for metabolic syndrome (AUC = 0.92)." (PMID 41187309, 2025). "Regarding metabolic syndrome, low adiponectin and high FSTL1 levels were each independently associated with the condition." (PMID 41187309, 2025). "The independent association of FSTL1 with metabolic syndrome may reflect inflammation and cardiovascular stress related to metabolic dysfunction." (PMID 41187309, 2025). "For the diagnosis of metabolic syndrome, a combined biomarker score was calculated as the logistic regression linear predictor, incorporating adiponectin, irisin, and FSTL1." (PMID 41187309, 2025). "Conversely, FSTL1 levels were significantly elevated in individuals with metabolic syndrome, consistent with recent findings identifying FSTL1 as a marker of unhealthy metabolic conditions." (PMID 41187309, 2025). "This study investigated the associations of circulating organokines (FABP4, FSTL1, adiponectin, and irisin) with CAD and metabolic syndrome in male patients undergoing elective coronary angiography." (PMID 41187309, 2025). "This research highlights FABP4 and FSTL1 as significant biomarkers associated with CAD and metabolic syndrome, respectively, while reaffirming the roles of adiponectin and irisin in metabolic regulation." (PMID 41187309, 2025). "The combination of adiponectin, FSTL1, and irisin as a biomarker strategy demonstrated high sensitivity and specificity for diagnosing metabolic syndrome (AUC = 0.92, 95% CI 0.88–0.96)." (PMID 41187309, 2025). "Both FSTL1 and adiponectin independently correlated with metabolic syndrome (P < 0.001, odds ratio 1.039, 95% CI 1.025–1.054; P < 0.001, odds ratio 0.979, 95% CI 0.971–0.988, respectively)." (PMID 41187309, 2025). "Our analysis revealed significant correlations between pre-surgery FSTL1 levels and total cholesterol, albumin, uricemia, and HDL values, indicating a link between FSTL1 and metabolic syndrome and inflammatory states." (PMID 38956222, 2024). "Six months post-surgery, FSTL1 levels correlate significantly with pre-surgery uricemia and HDL values, and marginally with post-surgery HDL and triglycerides, suggesting an association with metabolic syndrome and an inflammatory state rather than BMI or BS success alone." (PMID 38956222, 2024).
Myocardial fibrosis (4 papers, 2021 to 2026). "For example, delivery of Follistatin-like 1 (FSTL1) via an epicardial patch significantly improved cardiac Function and reduced myocardial fibrosis following IR injury in swine models." (PMID 41015973, 2025). "Increased exercise (56–66% of VO2max for 4 weeks)-induced Follistatin-like protein 1 (FSTL1) secretion through the FSTL1-USP10-Notch1 signaling axis has been reported to inhibit myocardial fibrosis in diabetic rats." (PMID 36036015, 2022). "Our present study revealed that FSTL1 protected cardiac function against MI-induced myocardial fibrosis in T2DM through a USP10/Notch1-dependent mechanism." (PMID 34957094, 2021). "Further in vitro analysis provided evidence that FSTL1 activated USP10/Notch1 signaling to inhibit myocardial fibrosis." (PMID 34957094, 2021). "Conversely, USP10 inhibition significantly offset the cardioprotective effect of FSTL1 by increasing myocardial fibrosis." (PMID 34957094, 2021). "FSTL1 treatment significantly reduced myocardial fibrosis and improved cardiac function by activating the Notch1 signaling pathway, which was reversed by Notch1 inhibitor." (PMID 34957094, 2021). "Further studies must investigate the molecular mechanism of FSTL1 in myocardial fibrosis with T2DM post-MI." (PMID 34957094, 2021). "Further, FSTL1 protected the heart against MI injury by decreasing myocardial fibrosis, and protected the heart from rupture by regulating cardiac fibroblast activation." (PMID 34957094, 2021). "In addition, in specific models of “MI plus type 2 diabetes,” exogenous supplementation or overexpression of FSTL1 reduced myocardial fibrosis and improved cardiac function through the USP10/Notch1 axis." (PMID 41602834, 2026). "The present study employed both in vivo and in vitro experiments to decipher the changes in Notch1 and USP10 and to evaluate the possible interaction between FSTL1 and USP10 in the pathological mechanism of MI-induced myocardial fibrosis in T2DM." (PMID 34957094, 2021). "The present study revealed that FSTL1 and USP10 were significantly activated in T2DM mice with MI, and FSTL1 treatment further increased USP10 activation and alleviating cardiac dysfunction by reducing myocardial fibrosis." (PMID 34957094, 2021). "In conclusion, FSTL1 treatment ameliorated cardiac dysfunction in MI with co-existent T2DM, possibly through inhibition of myocardial fibrosis and apoptosis by upregulating USP10/Notch1 signaling." (PMID 34957094, 2021). "Moreover, MI promoted myocardial fibrosis dramatically, by increasing collagen deposition and upregulated the expression of fibrotic markers including MMP9, collagen type I, and α-SMA, the effects of which were alleviated by FSTL1 administration." (PMID 34957094, 2021). "However, FSTL1 treatment alone did not elicit any effect on cardiac function, myocardial fibrosis, apoptosis, or serum LDH levels compared to sham group." (PMID 34957094, 2021).
systemic lupus erythematosus (4 papers, 2011 to 2022). An autoimmune multi-organ disease typically associated with vasculopathy and autoantibody production. "Serum FSTL1 levels were significantly elevated in patients with RA, ulcerative colitis, systemic lupus erythematosus, Sjögren's syndrome (SS), systemic sclerosis and polymyositis/dermatomyositis." (PMID 21303509, 2011).
chronic heart failure (3 papers, 2016 to 2021). "Thus, FSTL1 injections eliminated myocardial damage by inhibiting apoptosis and inflammatory responses, but patients with chronic heart failure had a high expression of FSTL1, which returned to normal after therapy." (PMID 34440203, 2021).
chronic obstructive pulmonary disease (3 papers, 2017 to 2023). A chronic and progressive lung disorder characterized by the loss of elasticity of the bronchial tree and the air sacs, destruction of the air sacs wall, thickening of the bronchial wall, and mucous accumulation in the bronchial tree. "We found that there were higher serum levels of FSTL1 in patients with PH related to chronic obstructive pulmonary diseases (COPD) and in mice model of hypoxia-induced PH (HPH)." (PMID 28361925, 2017). "Clinical research found that FSTL1 rose in serum of chronic obstructive pulmonary disease (COPD) patients combined with pulmonary hypertension and played a pivotal role during airway remodelling in the asthmatic patient." (PMID 36290379, 2022). "Recently, evidence has suggested that serum FSTL1 levels are markedly increased in patients with PH related to chronic obstructive pulmonary diseases (COPD) and that the lung expression of FSTL1 is upregulated in a hypoxia-induced PH mouse model." (PMID 38074873, 2023).
Cirrhosis (3 papers, 2020 to 2025). A chronic disorder of the liver in which liver tissue becomes scarred and is partially replaced by regenerative nodules and fibrotic tissue resulting in loss of liver function. "Our results showed that a high level of circulating FSTL1 is significantly correlated with therapeutic response in patients with cirrhosis." (PMID 40050288, 2025). "Consistent with previous findings, we observed that the FSTL1 levels were elevated in the serum of cirrhosis patients and in carbon tetrachloride (CCl4)-induced model mice and were positively correlated with the serum TGF-β1, TNF-α and IL-6 levels in cirrhosis patients." (PMID 40050288, 2025).
Disc Degeneration (3 papers, 2017 to 2021). "Our previous work revealed that FSTL1 is involved in disc degeneration and can promote inflammation in NP cells." (PMID 34190406, 2021). "In summary, knockdown of FSTL-1 can delay disc degeneration by inhibiting both the degradation of the disc matrix and the expression of inflammatory factors." (PMID 33936382, 2021). "MiR27a, which is up‐regulated by TNF‐α through the P38 pathway, blocks disc degeneration by targeting FSTL1 and can inhibit disc degeneration when expressed at high levels, thus providing a new potential therapeutic target for future treatment." (PMID 34190406, 2021). "Although FSTL-1 can promote inflammation, our original aim was to suppress inflammation and delay disc degeneration." (PMID 33936382, 2021). "To further investigate whether FSTL-1 can be a target for the treatment of IDD, we will suppress FSTL-1 and observe the degree of disc degeneration." (PMID 33936382, 2021). "Previous studies have shown that FSTL1 can promote IDD, and activation of the P38 pathway has also been reported to promote disc degeneration." (PMID 34190406, 2021). "Therefore, we established a mouse model of puncture-induced disc degeneration and analysed IVD tissues from FSTL-1+/- and C57/BL6 WT mice after 7 days." (PMID 33936382, 2021). "Therefore, we hypothesized that TNF‐α–induced increases in miR27a expression form a negative feedback loop to regulate disc degeneration by targeting FSTL1." (PMID 34190406, 2021).
endometrial cancer (3 papers, 2015 to 2021). Primary or metastatic malignant neoplasm involving the endometrium (mucous membrane that lines the endometrial cavity). "Supporting this, FSTL1 appears to play a tumour suppressor role in two other hormone-related women cancers (ovarian and endometrial cancer)." (PMID 26664652, 2015).
fibrosis (3 papers, 2017 to 2021). the formation of excess fibrous connective tissue in an organ or tissue in a reparative or reactive process. "Elevated levels of FSTL1 were found in plasma from patients with silicosis and in lungs of mice with silica-induced fibrosis." (PMID 31847129, 2019). "To provide clinical evidence for the increase Fstl1 level in samples from experimental silica-induced fibrosis, we determined whether expression and circulating level of FSTL1 were altered in patients with silicosis." (PMID 28341862, 2017).
intervertebral disc degeneration (3 papers, 2017 to 2021). "So we conclude that TNF‐α and FSTL1 engage in a positive feedback loop to promote intervertebral disc degeneration." (PMID 34190406, 2021). "In patients with intervertebral disc degeneration, serum FSTL1 levels were significantly higher than in the control group." (PMID 30644158, 2019). "More FSTL1-producing nucleus pulposus cells were observed in the intervertebral disc degeneration groups." (PMID 28498809, 2017). "Furthermore, FSTL1 expression was significantly increased in intervertebral disc degeneration models of rats." (PMID 28498809, 2017).
juvenile rheumatoid arthritis (3 papers, 2011 to 2016). "It has been reported that Fstl1 has a pro‐inflammatory activity and that its serum levels are elevated in juvenile rheumatoid arthritis." (PMID 27234440, 2016). "A recent report has shown that serum FSTL1 levels are slightly elevated in systemic onset juvenile rheumatoid arthritis." (PMID 21303509, 2011). "A recent study also reveals that serum FSTL1 levels are increased in systemic on-set juvenile rheumatoid arthritis (JRA) and suggests that FSTL1 may represent a biomarker of disease activity in systemic JRA." (PMID 22117761, 2011).
liver cirrhosis (3 papers, 2023 to 2025). "Taken together, our findings suggest that the serum level of FSTL1 is associated with the clinical response of liver cirrhosis patients to stem cells." (PMID 40050288, 2025). "We found that the serum level of FSTL1 was greater in patients with liver cirrhosis than in healthy controls, but there was greater variability among patients." (PMID 40050288, 2025). "To verify the correlation between therapeutic efficacy and the FSTL1 level, we recruited 58 patients with liver cirrhosis receiving stem cell transplantation." (PMID 40050288, 2025). "In summary, BMSCs alleviate liver cirrhosis by modulating the Creb3l1/lncRNA Kcnq1ot1/miR‐374‐3p/Fstl1 pathway." (PMID 37282819, 2023). "In conclusion, BMSCs alleviate liver cirrhosis by modulating the Creb3l1/lncRNA Kcnq1ot1/miR‐374‐3p/Fstl1 signaling pathway." (PMID 37282819, 2023). "Subsequently, we found that the lncRNA Kcnq1ot1/miR‐374‐3p/Fstl1 signaling pathway is involved in the progression of liver cirrhosis and can be regulated by BMSCs." (PMID 37282819, 2023). "BMSCs alleviate liver cirrhosis by modulating the Creb3l1/lncRNA Kcnq1ot1/miR–374–3p/Fstl1 signaling pathway." (PMID 37282819, 2023). "In summary, our findings reveal that FSTL1, which promotes early macrophage recruitment to facilitate subsequent effective macrophage accumulation during stem cell therapy, could potentially serve as a predictive biomarker of the response to stem cell therapy in patients with liver cirrhosis." (PMID 40050288, 2025). "Our data suggest that FSTL1 promotes early macrophage recruitment to facilitate subsequent effective macrophage accumulation during stem cell therapy, and could potentially serve as a predictive biomarker of the response to stem cell therapy in patients with liver cirrhosis." (PMID 40050288, 2025).
membranous nephropathy (3 papers, 2021 to 2024). "FSTL1 expression in the NEPTUNE cohort of humans with focal segmental glomerulosclerosis (FSGS), membranous nephropathy (MN), and IgA nephropathy (IgAN) was positively associated with age, eGFR, and proteinuria by multiple linear regression, as well as with interstitial fibrosis and tubular atrophy." (PMID 34502419, 2021). "By activating nuclear factor-kappa B (NF-κB) and wingless (Wnt)/β-catenin pathways, FSTL1 has been found to promote the progression of different forms of CKD, including focal segmental glomerular sclerosis(FSGS), membranous nephropathy (MN), immunoglobulin A (IgA) nephropathy (IgAN), etc.." (PMID 38390317, 2024).